STAT3 (signal transducer and activator of transcription 3)
Diseases named in the same sentence as STAT3 in open-access papers (continued):
Sharing a sentence is not in itself a finding about the gene and the disease.
diffuse large B-cell lymphoma (continued). "Beguelin and associates reported that IL-10 promotes tumor cell proliferation and survival by STAT3 signal pathway, and blocking of IL-10 receptor was suggested as a novel therapeutic target in diffused large B-cell lymphoma." (PMID 26528857, 2015). "We analyzed S1PR1/STAT3 pathway activation using immunohistochemistry in rituximab-treated diffuse large B-cell lymphomas (DLBCL; N = 103)." (PMID 25472725, 2014). "The signal transducer and activator of transcription 3 (STAT3) is a transcription factor that, when dysregulated, becomes a powerful oncogene found in many human cancers, including diffuse large B-cell lymphoma." (PMID 24142927, 2013). "The purpose of the study was to investigate the expression and prognostic value of STAT3 in diffuse large B-cell lymphoma (DLBCL)." (PMID 21806788, 2011). "Interestingly similar observations were made in diffuse large B-cell lymphoma (DLBCL) showing that STAT3 and NFAT2 interaction induced an immunoregulatory phenotype in malignant B cells with the upregulation of IL-10 and programmed Death-Ligand 1 (PDL1)." (PMID 35359922, 2022). "To show that AnnoMiner’s peak integration function can be used to integrate three different datasets in one analysis step, we re-analysed a data series published on STAT3 function in different forms of diffuse large B-cell lymphomas (DLBCL, GEO super-series GSE5072448)." (PMID 34326396, 2021). "Notably, a recent publication including ChIP-seq data from two diffuse large B-cell lymphoma cell lines shows STAT3 enrichment at this location in the IRF9 promoter, although, in this case STAT3 appeared to negatively regulate IRF9 transcription." (PMID 30679726, 2019). "Furthermore, a positive correlation between total STAT3 and Bcl-2pSer70 was observed in diffuse Large B cell lymphomas (N = 4) with a correlation coefficient of +0.9180." (PMID 26430964, 2015). "Artesunate induces apoptosis, autophagy, and ferroptosis in diffuse large B-cell lymphoma (DLBCL) cells by impairing STAT3 signaling." (PMID 38111578, 2023). "Studies have shown that the formation of NETs in diffuse large B-cell lymphoma directly upregulates toll-like receptor 9 pathway, thereby activating the STAT3, NF-κB, and p38 pathways to facilitate tumor progression, which suggests that NETs might be a prognostic marker for tumors." (PMID 36034958, 2022). "We previously reported that Fbw7 promotes apoptosis in diffuse large B-cell lymphoma (DLBCL) through Fbw7-mediated ubiquitination of Stat3." (PMID 35359405, 2022). "On the other hand, STAT3 supports amoeboid migration in diffuse large B-cell lymphoma (DLBCL), via ARHGEF2-RhoA signalling, whereby JAK inhibition reduces dissemination." (PMID 36699013, 2022). "Diffuse large B-cell lymphoma (DLBCL) cells also produce IL-10 to induce PD-L1 expression on DLBCL cells through the activation of the JAK2/STAT3 pathway." (PMID 34063096, 2021). "MYD88 mutations have been reported to be pathogenetically relevant in some cutaneous diffuse large B-cell lymphomas, leg type, and curiously seem to be mutually exclusive from other cancer-promoting mutations that activate the NF-κB pathway including BRAF, PIK3, or STAT3." (PMID 33333886, 2020). "We were able to detect expression of all four isoforms of STAT3 in eosinophils and diffuse large B-cell lymphoma (DLBCL) cells by qPCR analysis." (PMID 31861597, 2019). "Activated B-cell-like diffuse large B-cell lymphoma (ABC DLBCL) is characterized by increased expression and activator of signal transducer and activator of transcription 3 (STAT3)." (PMID 26727576, 2016). "We report a 37-year-old female with signal transducer and activator of transcription 3 (STAT3)-deficient HIES, diffuse large B-cell lymphoma (DLBCL) in remission, rituximab-induced hypogammaglobulinemia, and recurrent infections, who presented with acute-on-chronic dyspnea." (PMID 41769421, 2026).
diffuse large B-cell lymphoma (continued). "In addition to propofol, artesunate aggravated erastin-mediated ferroptosis by inhibiting STAT3 expression, exerting its antineoplastic effect on diffuse large B-cell lymphoma (DLBCL) in vitro." (PMID 36944609, 2023). "In diffuse large B-cell lymphoma, the expression of HLX was regulated by EBV-mediated STAT3 activation, and STAT3 was also confirmed to regulate the expression of HLX in Hodgkin lymphoma." (PMID 37719132, 2023). "STAT3 has been shown to activate HLX expression in cell lines derived from HL (L-540) and EBV-positive diffuse large B-cell lymphoma (DLBCL, DOHH-2/EBV)." (PMID 32922661, 2020). "STAT3 is constitutively activated in EBV-positive neoplasms, post-transplant lymphoproliferative diseases (LPDs), EBV-positive diffuse large B-cell lymphoma (DLBCL), nasopharyngeal cancer (NPC) cells, and extranodal NK/T-cell lymphoma (ENKL)." (PMID 30123428, 2018). "Growing evidence links the aggressiveness of non-Hodgkin’s lymphoma, especially the activated B cell-like type diffuse large B cell lymphomas (ABC-DLBCLs) to Toll-like receptor 9 (TLR9)/MyD88 and STAT3 transcription factor signaling." (PMID 29433938, 2018). "HDAC3 knockdown inhibits STAT3 (Tyr705) phosphorylation and survival of pSTAT3-positive DLBCL (Diffuse large B cell lymphoma cells)." (PMID 28968979, 2017). "In the resting state of diffuse large B-cell lymphoma (DLBCL) cells, HMGB1 co-localized and interacts with STAT3 in the nucleus." (PMID 28969092, 2017). "These isoforms, with or without Ser-701 inclusion, were required for optimal STAT3 function in ABC DLBCL (activated B-cell-like diffuse large B-cell lymphoma) cells." (PMID 37009804, 2023). "Furthermore, Gel-BLyS was shown to lead to downregulation of interleukin-6 receptor, a protein that is highly expressed in diffuse large B cell lymphoma (DLBCL) and impacts the STAT3 targets c-Myc, p21, Mcl-1, and Bcl-xL." (PMID 35744957, 2022). "Almost half of diffuse large B-cell lymphoma (DLBCL) tissues showed an increased expression of Pim kinases, which is even more frequent in the activated B-cell (ABC) subtype due to the constitutive activation of JAK/STAT3 signaling." (PMID 25491234, 2014). "In diffuse large B-cell lymphoma, small-molecule inhibition of STAT3, a transcriptional target of BCL6, has shown promise in chemotherapy-refractory activated B-cell-like DLBCL." (PMID 40805145, 2025). "Among others, a phase 1 trial (NCT01563302) revealed that systemic administration of danvartisen, an antisense oligonucleotide inhibitor of STAT3, reduced the levels of peripheral PMN-MDSCs in patients with diffuse large B-cell lymphoma (DLBCL)." (PMID 35158779, 2022). "In diffuse large B-cell lymphoma (DLBCL), a subgroup called the activated B cell–like (ABC) DLBCL, are characterised by high IL-6 expression and STAT3 activity and, importantly, are selectively sensitive to JAK inhibition when compared to germinal center B-cell (GCB) DLBCL." (PMID 31226168, 2019). "In situ and ex vivo analysis featured such tumours as activated type of diffuse large B cell lymphoma (ABC-DLBCL), expressing BCL2 and c-MYC, but not BCL6, with activated STAT3 signaling." (PMID 36503430, 2022).
endometrial cancer (88 papers, 2007 to 2026). Primary or metastatic malignant neoplasm involving the endometrium (mucous membrane that lines the endometrial cavity). "Autocrine activation of JAK/STAT3 signal by OSM in ARID1A-deficient endometrial cancer cells promotes PLK1 levels, inducing mitotic abnormality." (PMID 41800254, 2026). "We here employed a synthetic lethal drug screen for ARID1A and found that JAK/STAT3 pathway is a therapeutic vulnerability in ARID1A-deficient endometrial cancer." (PMID 41800254, 2026). "Subsequent findings established that leptin signaling was implicated in promotion of endometrial cancer cell proliferation by activating STAT3 and ERK2 pathways and that leptin-induced phosphorylation of ERK2 and Akt was determined by STAT3 activation." (PMID 36674935, 2023). "Several studies have shown that elevated STAT3 expression occurs in both endometriosis and endometrial cancer, suggesting STAT3 is a potential risk factor for both diseases." (PMID 33436679, 2021). "Studies have shown that OSM promotes the invasion and angiogenesis of endometrial cancer by activating STAT3, which is linked with tumor cell proliferation, survival, and metastatic invasion." (PMID 31871447, 2019). "PTPRD acts in the STAT3 pathway, which has been implicated in both endometriosis and endometrial cancer." (PMID 29608257, 2018). "Increased expressions of antiapoptotic Bcl-xL, survivin and Mcl-1 are strongly associated with the elevated p-Stat3 (Tyr705) in cervical and endometrial cancer tissues." (PMID 17311011, 2007). "IL-17, as a potent pro-inflammatory cytokine, is closely associated with the formation, growth, and metastasis of various tumors, promoting tumor growth by activating proliferation-related pathways in endometrial cancer cell, such as NF-κB and STAT3." (PMID 39367897, 2025). "It has been found to have an antineoplastic role in endometrial cancer through effects on Jak1 and STAT3 signaling." (PMID 40686703, 2025). "The mRNA level of CDH5 was significantly correlated with JAK1 and STAT3 levels in endometrial cancer." (PMID 38459564, 2024). "In cases of endometrial cancer, STAT3 inhibition reduces primary cell viability, proliferation, and invasion, impairing not only tumor development but also metastasis." (PMID 39188680, 2024). "STAT3 levels are elevated in endometrial cancer cells, particularly the serine-phosphorylated form, phospho-STAT3 Ser727." (PMID 39596005, 2024). "Recent studies have also shown that the JAK/STAT3 pathway is upregulated in endometriosis and can be used as a treatment target for endometrial cancer." (PMID 39650066, 2024). "The most well-known traditional activator of the JAK/STAT3 pathway is interleukin-6 (IL-6), indicated as the most significant ligand with carcinogenic potential, which also contributed to endometrial cancer development." (PMID 39188680, 2024). "Taken together, these findings suggest that STAT3 can directly activate CDH5 transcription by binding to its promoter region in endometrial carcinoma and that IL-10 can further promote transcription." (PMID 38459564, 2024). "IL-11 regulates endometrial cancer cell adhesion and migration via upregulating the phosphorylated (p)-STAT3 protein abundance." (PMID 37153732, 2023). "The lncRNA PCGEM1 is a relatively novel lncRNA, and a previous study demonstrated that PCGEM1 is capable of enhancing endometrial carcinoma cell proliferation and apoptosis by targeting STAT3 via sponging of miR-129." (PMID 36915057, 2023). "One study showed that miR-149-5p was modulated by circular RNA (circRNA), i.e., hsa_circ_0061140, which promoted endometrial carcinoma progression by regulating the miR-149-5p/Stat3 pathway." (PMID 37240034, 2023). "PCGEM1 also enhances endometrial carcinoma cell proliferation and apoptosis by targeting STAT3 via downregulation of miR-129." (PMID 36915057, 2023). "Hesperidin was predicted to slow the growth of endometrial carcinoma cells by downregulating STAT3 activation." (PMID 37446814, 2023).
endometrial cancer (continued). "STAT3 was reported to be upregulated in early-stage endometrial cancer, and inhibition of its signaling pathway has been shown to repress endometrial cancer stem cells and tumor growth." (PMID 35328698, 2022). "Silibinin reduces endometrial cancer cell growth, produces cell cycle arrest, and promotes cell death through reducing STAT3 phosphorylation expression." (PMID 36072980, 2022). "In endometrial cancer, leptin activates STAT3 proteins, which increase their activity in the process of oncogenesis by stimulating proliferation, promoting angiogenesis, and avoiding the control of the immune system." (PMID 35628118, 2022). "A study on an endometrial cancer cell line showed that activated STAT3 proteins overexpress anti-apoptotic genes, such as Bcl-xL and Mcl-1, rendering these cells immortal and chemo-resistant." (PMID 35628118, 2022). "Has_circ_0061140 was also show to enhance the progression of endometrial carcinoma by targeting the miR-149/signal transducer and activator of transcription 3 (STAT3) axis." (PMID 35130798, 2022). "• Establishment of endometrial cancer organoid model.• Novel STAT3 inhibitors as potent anticancer agent." (PMID 33959613, 2021). "Targets of miRNA-337-3p include STAT3, which is upregulated by multiple miRNAs, long noncoding RNAs and circular RNAs, and drives endometrial cancer development, progression and metastasis." (PMID 33920951, 2021). "According to Peixin Dong, NEAT1 facilitated the progression of aggressive endometrial cancer by repressing miR-361 expression and increasing STAT3 signalling." (PMID 33546665, 2021). "The obtained results showed that leptin siRNA inhibited the expression of JAK2 and STAT3 proteins both in the Ishikawa culture untreated with cisplatin (0 h) and the endometrial cancer culture incubated with cisplatin for 12, 24 and 48 h." (PMID 32531934, 2020). "Next, we examined the variances in the mRNA and protein expression of JAK2 and STAT3 in the Ishikawa endometrial cancer cells treated with 5 μM of cisplatin and 10–40 ng/mL of leptin." (PMID 32531934, 2020). "The results showed that cisplatin reduces the transcriptional activity of selected genes, while leptin promoted the expression of mRNA JAK2 and STAT3 in endometrial cancer cells (p < 0.05)." (PMID 32531934, 2020). "The phospho-STAT3 then directly binds to promoter sequence of miR-204-5p, resulting in increased clonogenic proliferation, migration and invasion in endometrial carcinoma, via a feed-backward-loop (FBL) motif of TF-miRNA-target gene." (PMID 32102656, 2020). "Adipose-derived IL-6 can promote the proliferation, invasion and angiogenesis of endometrial cancer cells by activating the JAK/STAT3 signaling pathway." (PMID 31440472, 2019). "Leptin also promotes the proliferation and invasion of endometrial cancer cells by activating STAT3 and ERK1/2, JNK signaling pathways." (PMID 31440472, 2019). "It activates migration and invasion of endometrial cancer cells through the STAT3 signaling pathway." (PMID 30559930, 2018). "The present study found that high glucose concentrations increase expression of STAT3 and its target proteins in grade 1 endometrial cancer cells." (PMID 28114390, 2017). "The present study supports this possibility, as high glucose treatment was found to up-regulate STAT3 and its target genes in type 1 endometrial cancer cells." (PMID 28114390, 2017). "We and others previously determined that IL11 mRNA and protein are up-regulated in endometrial tumour tissue and uterine lavage in women and we have shown that IL11 alters endometrial cancer cell function in vitro, via STAT3." (PMID 28186993, 2017). "Based on our pilot data that showed a high glucose-mediated increase in STAT3 in grade 1 endometrial cancer cells, we aimed to evaluate a potential inhibitor of such STAT3 activation." (PMID 28114390, 2017).
endometrial cancer (continued). "We have previously reported that constitutive expression of pSTAT3 occurs in human endometrial tumor tissues and endometrial cancer cell lines; other studies have shown that consistent STAT3 expression regulates the endometrial cancer growth and angiogenesis." (PMID 28114390, 2017). "In Ishikawa (grade 1) endometrial cancer cells subjected to media with low, normal, or high concentrations of glucose, expression of STAT3 and its target proteins was evaluated by real-time quantitative PCR (qPCR)." (PMID 28114390, 2017). "A number of signaling pathways, including MAPK/ERK, PI3K/AKT and JAK/STAT3 pathways, are constitutively activated and play important roles in the growth and progression of endometrial cancer." (PMID 28986550, 2017). "In conclusion, we have demonstrated a relationship between a high-glucose environment and STAT3 activation in type 1 endometrial cancer cells." (PMID 28114390, 2017). "In the present study we show that metformin suppresses both pSTAT3 Ser727 and total STAT3 expression in a grade 1 endometrial cancer cell line cultured in high glucose media." (PMID 28114390, 2017). "This study helps contribute to the understanding of these mechanisms, showing that high glucose concentrations alter expression of STAT3 and its target proteins in type 1 endometrial cancer cells." (PMID 28114390, 2017). "We also observed that metformin affects grade 1 endometrial cancer cell growth, apoptosis induction, and inhibits STAT3 and its target proteins in both in vitro and in vivo (with a murine xenograft model)." (PMID 28114390, 2017). "The downstream signaling of JAK2/STAT3 pathway activates several mechanisms responsible for the progression of ovarian and endometrial carcinomas." (PMID 28686225, 2017). "We demonstrated herein that the oncogenic effects of autocrine hGH and hPRL in HCC cells were mediated by STAT3 concordant with the previous report in endometrial carcinoma." (PMID 27102295, 2016). "STAT3 has been reported to be the target gene of miR-124 in endometrial cancer cells, and be involved in the miR-124-mediated suppressive effects on endometrial cancer cells." (PMID 25928665, 2015). "Nevertheless, these data suggest that TrkB-dependent STAT3 activation is an important event in regulating miR-204 transcription in endometrial cancer cells and possibly other cancer types." (PMID 24321270, 2013). "Human papillomavirus-immortalised cervical cell line (Ect1/E6E7), C33A and all three endometrial cancer cell lines, RL-95-2, Ishikawa, and Hec-1B express low or detectable levels of Stat3 phosphorylation." (PMID 17311011, 2007). "Concurrence of elevated p-Stat3 (Tyr705) and p-Stat3 (Ser727) is high with 76.9% (20/26) and 63.6% (7/11) in cervical and endometrial cancers, respectively." (PMID 17311011, 2007). "Our results showed that elevated levels of the phosphorylation (Tyr705) of Stat3 protein were detected in the nuclei of 24 out of 115 total endometrial cancer specimens." (PMID 17311011, 2007). "Although none of the three endometrial cancer cell lines we studied expressed elevated Stat3 phosphorylation, 20.8% of 115 total endometrial cancer specimens showed elevated levels of Stat3 phosphorylation." (PMID 17311011, 2007). "Our results indicated that elevated phosphorylation of Stat3 was detected in cervical and endometrial cancer cell lines." (PMID 17311011, 2007). "Therefore, STAT3 has become a promising marker and potential therapeutic target in various types of cancers, such as lung, prostate, pancreatic, breast, and endometrial cancer." (PMID 39188680, 2024). "Further analysis of the gene alterations in the CBioPortal database revealed, as shown in the total gene alteration histogram, that embryonic tumors, endometrial carcinoma, and mature B-cell lymphoma are the top three cancers with the highest frequency of STAT3 alteration." (PMID 37724127, 2023).